LPL (lipoprotein lipase)
Diseases named in the same sentence as LPL in open-access papers (continued):
Sharing a sentence is not in itself a finding about the gene and the disease.
lupus (8 papers, 2006 to 2025). "Antibodies to lipoprotein lipase have been reported in systemic lupus erythematosus and are associated with increased TG levels." (PMID 35733062, 2022). "In fact, anti-LPL antibodies were identified in approximately 40% of lupus patients and were associated with high triglycerides (TGs) levels." (PMID 19606253, 2009). "Antilipoprotein lipase (anti-LPL) antibodies have been recently described in rheumatic diseases, mainly in systemic lupus erythematosus (SLE) and systemic sclerosis (SSc) but also in polymyositis and rheumatoid arthritis." (PMID 19606253, 2009). "As the authors of this report note, it is not known whether the presence of prematurely truncated LPL peptide due to the variant triggered the autoimmune response against LPL, but autoantibodies against LPL have been found in patients with autoimmune diseases, such as systemic lupus erythematosus." (PMID 39858602, 2025). "In addition, LPL is known to be upregulated in patients with systemic lupus erythematosus." (PMID 36982268, 2023).
nephrotic syndrome (8 papers, 2020 to 2025). A collection of symptoms that include severe edema, proteinuria, and hypoalbuminemia; it is indicative of renal dysfunction. "The presence of nephrotic syndrome is associated with a significant reduction in both the abundance and activity of the LPL protein." (PMID 38911039, 2024). "In nephrotic syndrome, mechanistically, increased LDL synthesis and reduced LDL catabolism due to impaired lipoprotein lipase activity have been proposed as underlying mechanisms." (PMID 41439970, 2025). "Because HDL dysfunction in nephrotic syndrome could result in impaired LPL-mediated lipolysis of triglycerides-rich lipoproteins, this process plays a key role in dysregulating triglycerides-rich lipoprotein." (PMID 35883502, 2022). "Another intermediary in LPL deficiency is represented by ANGPTL4, a glycoprotein expressed in several tissues that physiologically inhibits LPL activity and is upregulated in nephrotic syndrome as emerging studies have demonstrated, thus contributing to hypertriglyceridemia pathogenesis." (PMID 33916487, 2021). "Consequently LPL-mediated lipolysis of VLDL and chylomicrons is inadequate and causes the progressive accumulation of serum triglycerides, the increase of VLDL triglycerides content, the impaired clearance of chylomicrons and the lipemia post-meal observed over nephrotic syndrome." (PMID 33916487, 2021). "Several studies have shown a lack of LPL in nephrotic syndrome probably due to post-transcriptional or post-translational alterations involving also its cofactor GPIHBP1." (PMID 33916487, 2021).
ovarian carcinoma (8 papers, 2013 to 2024). A malignant neoplasm originating from the surface ovarian epithelium. "The level of lipoprotein lipase (LPL), required for hydrolytic release of fatty acids from triacylglycerols in circulating lipoprotein particles, lowered by 78% in ovarian cancer." (PMID 36012230, 2022). "A study reported that the amount of lipoprotein lipase (LPL) in EVs produced from ovarian cancer cells was shown to be considerably higher than in ovarian surface epithelial cells, indicating that LPL may be useful in the early detection of ovarian cancer." (PMID 39611045, 2024). "Based on TCGA, higher FABP4 and LPL and lower TFAM expression indicated poorer overall survival in patients with ovarian cancer." (PMID 36012230, 2022). "Noticeably, a very recent study showed the higher concentration of lipoprotein lipase (LPL) and collagen type V alpha 2 chain (COL5A2) in exosomes derived from ovarian cancer cells (SKOV-3) compared to ovarian surface epithelial cells (HOSEPiC) by proteomic and lipidomic analysis." (PMID 33671587, 2021).
Sepsis (8 papers, 2017 to 2025). Sepsis is defined as life-threatening organ dysfunction caused by a dysregulated host response to infection. "A similar result was noted for SNPs that reduce the activity of LPL regarding the protective effect against sepsis risk(IVW method: OR 0.854, 95% CI 0.771–0.946; P = 0.002." (PMID 40934270, 2025). "The high levels of endotoxins present in severe sepsis can inhibit the activity of lipoprotein lipase (LPL), causing an increased triglyceride in plasma." (PMID 39054513, 2024). "Moreover, genetic mimicry near the ANGPTL3 and LPL gene suggested that reducing the activity of ANGPTL3 and LPL (mimicking antisense anti-ANGPTL3 and LPL agents) was forecasted to decrease sepsis risk." (PMID 40934270, 2025). "Notably, we have identified ANGPTL3 and LPL as potential drug targets that significantly lowered the risk of sepsis." (PMID 40934270, 2025). "Additionally, only TG-lowering genetic variants in ANGPTL3 and LPL were associated with lower sepsis risk in our study." (PMID 40934270, 2025). "Within the 9 lipid-lowering drug targets investigated ANGPTL3 and LPL exhibit potential as candidate drug targets for sepsis." (PMID 40934270, 2025). "VLDL levels increase due to reduced clearance and metabolic conversion under conditions of sepsis, and it is recognized that reduced lipoprotein lipase activity is a major contributor to this condition." (PMID 36551906, 2022). "Our study provided strong evidence that ANGPTL3 and LPL are promising drug targets for sepsis." (PMID 40934270, 2025). "Moreover, this study demonstrates that ANGPTL3 and LPL are promising candidate drug targets for the treatment of sepsis." (PMID 40934270, 2025). "However, plasma triglyceride level is increased in sepsis because of suppressed plasma lipoprotein lipase activity." (PMID 28831223, 2017). "However, in patients with sepsis, hypolipidemia is usually found, and the possible mechanism behind this lipid alteration is a tissue lipoprotein lipase inhibition, an upregulated hepatic TG production, disruption of the synthesis-utilization balance and interaction with cytokines or endotoxins." (PMID 34045976, 2021).
heart failure (7 papers, 2017 to 2025). Inability of the heart to pump blood at an adequate rate to meet tissue metabolic requirements. "In contrast, the loss of cardiac LPL also causes heart failure." (PMID 34356640, 2021). "These experiments in genetically modified models suggest that disturbing cardiac LPL is sufficient to induce cardiac failure." (PMID 34356640, 2021).
melanoma (7 papers, 2013 to 2025). A malignant, usually aggressive tumor composed of atypical, neoplastic melanocytes. "Further investigations have elucidated its capacity to inhibit lipoprotein lipase derived from melanoma, thereby modulating systemic lipid metabolism through the suppression of lipoprotein lipase activity." (PMID 40969371, 2025). "LPL, CD36, FATP1 (SLC27A1), and FATP2 (SLC27A2), implicated in increased FA uptake into melanoma cells, are unaffected by point mutation in cancer and display gene amplification in 2%–8% of cases." (PMID 35732120, 2022). "Elevated expression of one dysregulated gene, the lipoprotein lipase LPL, accelerated melanoma onset in zebrafish." (PMID 32455885, 2020).
non-small cell lung carcinoma (7 papers, 2012 to 2026). A group of at least three distinct histological types of lung cancer, including non-small cell squamous cell carcinoma, adenocarcinoma, and large cell carcinoma. "LPL encodes a protein lipase; high expression of LPL predicts poor prognosis in non-small cell lung cancer and can be highly expressed in tumor-associated macrophage subsets." (PMID 36712848, 2022). "We employed the scCancerExplorer database to analyze single-cell data and evaluate the expression profiles of the LPL gene in non-small-cell lung cancer as well as in adjacent normal tissues." (PMID 40427755, 2025). "In patients with resectable non-small cell lung cancer, high levels of LPL activity have been detected in cancer tissue." (PMID 23110339, 2012). "Similarly, using the IncuCyte® S3 live-cell analysis system, we observed that Ibrolipim significantly suppressed the proliferative activity of H1299 cells, also suggesting the important role of LPL in non-small-cell lung cancer." (PMID 40427755, 2025). "In non-small-cell lung cancer (NSCLC) tumor cells, enzymes such as lipoprotein lipase (LPL) are known to use triacylglycerols (TAGs) and phospholipids (PLs) from the bloodstream to acquire energy for membrane synthesis and tumor proliferation via lipolysis." (PMID 34436478, 2021). "Moreover, increased LPL activity in non-small cell lung cancer tissue predicts shorter patient survival, independent of standard prognostic factors." (PMID 23110339, 2012).
type 1 diabetes (7 papers, 2012 to 2026). "This study reported that the upregulation of lipoprotein lipase (LPL) activity upon experimental induction of type-1 diabetes in rats is PKD1 dependent." (PMID 29930945, 2018). "Data gathered through microarray profiling of placenta samples has indicated that type 1 diabetes is associated with a 2.4-fold up-regulation of FABP4 compared to control, however, LPL expression was down-regulated nearly 3.4-fold." (PMID 25222554, 2014). "For instance, LPL upregulation may be confined to specific animal models of type-1 diabetes, while CD36 downregulation may be a characteristic feature of the pressure-overloaded heart." (PMID 29930945, 2018). "We further investigated whether type 1 diabetes affected the transcription of genes involved in lipid metabolism such as fatty acid synthase (FASN), lipoprotein lipase (LPL) and hormone-sensitive lipase (HSL) in each depot." (PMID 25170835, 2014). "However, its impact on lipoprotein lipase (LPL) and the sources of FA for cardiac use in Type 1 diabetes is unknown." (PMID 41788807, 2026). "An important argument against an involvement of LPL in insulin secretion is that insulin-dependent diabetes is not a commonly reported problem in animal models of LPL deficiency, or in patients with either total LPL deficiency or with non-functional LPL protein." (PMID 23186339, 2012).
angina (6 papers, 2018 to 2025). "Researchers from the REGRESS study group demonstrated that LPL activity was inversely associated with severity of angina pectoris." (PMID 32673331, 2020). "Single cell integration prioritized PAM for stable angina pectoris and ventricular arrhythmia and LPL for peripheral artery disease, whose transcriptional expressions were enriched in cardiomyocytes." (PMID 40657554, 2025). "Single cell integration further prioritized PAM for stable angina pectoris and ventricular arrythmia and LPL for peripheral artery disease, whose transcriptional expressions were enriched in cardiomyocytes." (PMID 40657554, 2025). "Investigating the role of LPL rs264, PROCR rs867186 and PDGF rs974819 gene polymorphisms in the pathogenesis of unstable angina requires further multicenter studies." (PMID 38392646, 2024). "In this study, we examined the distribution of the LPL rs264, PROCR rs867186 and PDGF rs974819 polymorphisms between patients with unstable angina and control subjects." (PMID 38392646, 2024). "The aim of the study was to examine the associations between the LPL rs264, PROCR rs867186 and PDGF rs974819 gene polymorphisms and the risk of unstable angina and selected clinical parameters." (PMID 38392646, 2024). "FFDS has demonstrated its potential in reducing circulating TG levels and angina frequency in patients with SCHD, which may be due to the active ingredients of FFDS acting on LPL, CD36, FABPpm, L-FABP, LCAT, and CEPT." (PMID 39944604, 2025).
breast tumor (6 papers, 2014 to 2024). "The lipid obtained via LPL in the breast tumor microenvironment may thus promote breast tumor growth and development." (PMID 36652113, 2023). "Decrease in FAS and LPL enzymes which provide fatty acids for breast tumor growth." (PMID 33071773, 2020). "SHC2, LPL, PCK1, and KRT6B were all under-expressed, and only SFRP2 was highly expressed in the breast tumor." (PMID 38791477, 2024). "Along the same lines, clinical breast tumor specimens appear to universally co-express LPL and FASN irrespective of their biomarker status." (PMID 25215509, 2014).
Cachexia (6 papers, 2019 to 2025). Severe weight loss, wasting of muscle, loss of appetite, and general debility related to a chronic disease. "Furthermore, cachexia is associated with a reduction in the lipogenesis rate and a decrease in the activity and expression of lipoprotein lipase (LPL)." (PMID 39596015, 2024). "It is suggested that the initial rise in LPL activity provides more oxidation of fatty acids in cachexia state." (PMID 37205195, 2023). "LPL modulators such as tumour necrosis factor (TNF)-α, Interleukins (IL-1, IL-6) induce by cachexia which obstructs the activity of LPL foremost to a stark cut in the accumulation of fatty tissues." (PMID 32847584, 2020). "Several metabolic alterations occur in adipose tissue in cancer cachexia patients: an increase in lipolysis; a decrease in lipoprotein lipase activity; and de novo lipogenesis enzymes." (PMID 31741709, 2019). "Remodelling from white adipose tissue to brown adipose tissue in cachexia might contribute to increased energy requirements, and decreased lipoprotein lipase activity in white adipose tissue accelerates fat atrophy in patients with cachexia." (PMID 40641114, 2025). "These evidences suggest that the dysfunction of LPL is related to the occurrence and development of CAC, and testing the activity of LPL may be useful for the diagnosis of cachexia." (PMID 37205195, 2023). "In cancer-cachexia, adipose tissue suffers excessive lipolysis, decreased lipogenesis de novo and uptake of fatty acids from triacylglycerol from lipoproteins by a reduction on activity of lipoprotein lipase." (PMID 31741709, 2019). "Indeed, in cachexia proinflammatory cytokines (mainly TNF-α and IL-6) directly influence adipocyte metabolism by decreasing the activity of lipoprotein lipase (LPL), an enzyme that regulates the uptake of circulating triglycerides into adipocytes." (PMID 33809200, 2021).
chronic kidney disease (6 papers, 2013 to 2026). Impairment of the renal function secondary to chronic kidney damage persisting for three or more months. "LPL is a lipoprotein lipase that is protective in patients with chronic kidney disease with impaired plasma VLDL lipolysis." (PMID 36104709, 2022). "Increased levels of TG can be observed in chronic renal failure patients, a result of low activity of lipoprotein lipase (LPL) which facilitates clearance of TG and reduction of TG levels." (PMID 36045354, 2022). "However, the predictor of a pre-LpL mass as a CAD event in patients with chronic kidney disease (CKD) remains unclear." (PMID 41822820, 2026).
colorectal cancer (6 papers, 2012 to 2025). A primary or metastatic malignant neoplasm that affects the colon or rectum. "In patients with colorectal cancer, a significant reduction in gene expression and activity levels of lipoprotein lipase (LPL) and FASN was detected in adipose tissue adjacent to the tumor lesion compared to tissue distant from the neoplasm." (PMID 36670988, 2023). "Decreased activity of LPL has been found during tumor growth in mice as well as in patients suffering from gastric and colorectal carcinoma." (PMID 34621740, 2021). "While, the decreased levels of lipogenic enzymes Lipoprotein lipase (LPL) and Fatty acid synthase (FAS), important components of the regulation of lipolysis in adipocytes pathway was reported to be associated with colorectal cancer." (PMID 28587194, 2017).
gestational diabetes mellitus (6 papers, 2019 to 2024). "In gestational diabetes mellitus, an increase in maternal lipid profile may cause the accumulation of fetal fat as it increases the activity of lipoprotein lipase, which results in a higher rate of fatty acid transfer through the placenta." (PMID 37964879, 2023). "Our results highlight an increased expression of LRP1 and LPL in placentas of insulin-treated gestational diabetes and, in turn, an increase in the intracellular ROH apparatus by the non-STRA6 pathway." (PMID 34945773, 2021).
lipodystrophy (6 papers, 2014 to 2025). A congenital or acquired disorder characterized by abnormal loss or redistribution of the adipose tissue in the body. "For example, we saw adipose-specific TG and HDL colocalizations for both KLF14 and LPL, two genes assigned previously to a lipodystrophy cluster that has been shown to overlap with IR biology." (PMID 35292083, 2022). "Our results revealed that FSH induced the upregulation of PPAR, C/EBP, LPL, FAS and perilipin in adipocytes; this result suggested that FSH-induced excessive lipid biosynthesis in adipose tissue might cause lipodystrophy and cause spillover from adipocytes." (PMID 25754247, 2015). "Studies show that phosphoenolpyruvate carboxykinase promoter activation could lead to the development of lipodystrophy, due to the extreme level of lipid droplets in the brown adipose tissue while the high level of lipoprotein lipase may induce assimilation of triglycerides." (PMID 35328389, 2022). "LPL further colocalized with WHR in adipose tissue, the main tissue characterizing the lipodystrophy phenotype." (PMID 35292083, 2022).
liposarcoma (6 papers, 2007 to 2021). A usually painless malignant tumor that arises from adipose tissue. "Recent findings have revealed that breast and liposarcoma cancers have both de novo fatty acid synthesis pathways and lipoprotein lipase-mediated extracellular lipolysis." (PMID 32503508, 2020).
arteriosclerosis (5 papers, 2011 to 2022). A vascular disorder characterized by thickening and hardening of the walls of the arteries. "Increased lipoprotein lipase activity in the endothelium seems to increase the risk of arteriosclerosis, whereas increased activity in muscle and fat tissue seems to lower the risk." (PMID 23724225, 2011). "LPL is a lipid metabolism gene and a risk factor for arteriosclerosis." (PMID 35832544, 2022). "Consequently, ANGPTL4 not only regulated TC by inhibiting LPL, but also affected serum lipid levels and arteriosclerosis by other pathways." (PMID 30323852, 2018).
coronary atherosclerosis (5 papers, 2018 to 2023). Atherosclerosis of the coronary vasculature. "Angiopoietin-like 4 (ANGPTL4) is an endogenous inhibitor of lipoprotein lipase that modulates lipid levels, coronary atherosclerosis risk, and nutrient partitioning." (PMID 29899519, 2018).